Y_RNA (Y RNA )
Gene: Miscellaneous RNA gene on chromosome 4 (185,709,873 to 185,709,967, reverse strand). Ensembl gene ENSG00000207497.
Homologues: Orthologues: chimpanzee Y_RNA (99% identical), macaque Y_RNA (92% identical), zebrafish Y_RNA (68% identical). Paralogues in human: Y_RNA (76% identical), RNY1P5 (75% identical), Y_RNA (75% identical), Y_RNA (74% identical), Y_RNA (73% identical), RNY1P1 (72% identical), Y_RNA (72% identical), RNY1P14 (71% identical), Y_RNA (71% identical), RNY1P11 (69% identical), Y_RNA (69% identical), RNY1 (68% identical), and 83 more.